CRP (C-reactive protein)
Diseases named in the same sentence as CRP in open-access papers (continued):
Sharing a sentence is not in itself a finding about the gene and the disease.
COVID-19 (continued). "Accordingly, the results of the present study demonstrated that patients with severe COVID-19 had higher levels of several inflammatory biomarkers (e.g., NLR, CRP, procalcitonin, PCT, IL-6, and IL-10 levels)." (PMID 33763027, 2021). "COVID-19 Egyptian patients with ARDS showed lymphopenia, increased thrombotic activity, elevated CRP, LDH, and ferritin levels." (PMID 33861750, 2021). "Lower hemoglobin (p = 0.034) and lower CRP (p = 0.004) at hospital admission and nephrotoxin exposure (p < 0.001) were also independent predictors for the development of AKD in COVID-19-AKI patients in the multivariable analysis." (PMID 34640618, 2021). "In this study, we performed a meta-analysis of clinical studies reporting stroke history, intensive inflammatory response, and procoagulant state C-reactive protein (CRP), Procalcitonin (PCT), and coagulation indicator (D-dimer) in patients with COVID-19." (PMID 33732102, 2021). "Age, diabetes, coronary heart disease (CHD), percentage of lymphocytes (LYM percent), procalcitonin (PCT), serum urea, CRP, and D-dimer were found to be correlated with mortality by LASSO binary logistic regression in a total of 2529 COVID-19 patients." (PMID 34573923, 2021). "The present study shows that CRP, LDH, ferritin and IL-6 are related not only with COVID-19 severity but also with mortality." (PMID 34439469, 2021). "The data we have shown are in line with these findings since the number of lymphocytes and CRP levels as well as LDH and PaO2/FIO2 correlated with patient prognosis assessed by the LOS and number of deaths from COVID-19." (PMID 34163490, 2021). "Longitudinal CRP and PCT concentrations and trajectories of 237 hospitalised patients with COVID-19 were modelled." (PMID 34496795, 2021). "Assess Efficacy of HB-adMSCs to treat COVID-19 patients.Primary endpoints: detect change from baseline in inflammatory markers (IL-6, IL-10, TNF-alpha, C Reactive protein), improving oxygenation, and decreasing time to return to room air (RTRA)." (PMID 33815867, 2021). "Age, diabetes, coronary heart disease (CHD), percentage of lymphocytes (%LYM), procalcitonin (PCT), serum urea, CRP, and D-dimer were found to be correlated with mortality by LASSO binary logistic regression in a chort of 2,529 COVID-19 patients." (PMID 34786318, 2021). "We showed that patients hospitalized with COVID-19 having a history of VTE, predischarge CRP level greater than 10 mg/mL, or peak D-dimer level during hospitalization greater than 3 μg/mL were predisposed to experience new onset of VTE after discharge." (PMID 34807256, 2021). "Consistently, Zhao and colleagues reported that CRP, IL6, LDH and ferritin increased dramatically in COVID-19 patients, leading to disease progression." (PMID 34578138, 2021). "Previous studies showed that severe or critical COVID-19 patients were older, had more comorbidities, higher levels of LDH, D-dimer, CRP, and lower levels of ALB, lymphocyte count." (PMID 34372792, 2021). "Significantly higher levels of alanine aminotransferase (ALT), aspartate aminotransferase (AST), C-reactive protein (CRP), and lactate dehydrogenase (LDH) were found in the COVID-19 group compared to the control group (P < 0.05)." (PMID 34691316, 2021). "Correlation of both NLR and PLR with already established inflammatory markers such as CRP, ESR, and those specific for COVID-19 (ferritin, D-dimers, and eosinophils) was also evaluated." (PMID 34181675, 2021). "As compared with the GPS (which includes the CRP level and lymphocyte count), the PNI had significantly higher accuracy in predicting critical illness due to COVID-19." (PMID 33521032, 2020). "We found that D-dimer, CRP, LDH, procalcitonin, sodium, urea, and creatinine all had significantly vital roles in the invasive ventilation of COVID-19 patients." (PMID 32999777, 2020).
COVID-19 (continued). "ALT (AUC = 0.879), CRP (AUC = 0.870), NEU (AUC = 0.858), LDH (AUC = 0.835), and Urea (0.835) had very good accuracy in predicting cases with positive RT-PCR for COVID-19, respectively." (PMID 32259132, 2020). "Comparison of hematological parameters between mild and severe cases of COVID-19 showed significant differences in interleukin-6 (IL-6), D-Dimer, glucose (GLU), thrombin time (TT), fibrinogen (FIB) and C-reactive protein (CRP)." (PMID 32259132, 2020). "H7N9 patients had similar patterns of lymphopenia, neutrophilia, elevated alanine aminotransferase, C-reactive protein, and those seen in H1N1 patients, which were all significantly different from patients with COVID-19 (P < 0.01)." (PMID 33261654, 2020). "ALT (AUC = 0.879), CRP (AUC = 0.870), NEU (AUC = 0.858), LDH (AUC = 0.835), and Urea (AUC = 0.835) had very good accuracy in predicting cases with positive RT-PCR for COVID-19, respectively." (PMID 32259132, 2020). "Based on the findings of this study ALT, CRP, NEU, LDH, and Urea have very good accuracy in predicting cases with positive RT-PCR for COVID-19, respectively." (PMID 32259132, 2020). "After tocilizumab treatment, the seven severe COVID-19 patients exhibited decreased serum PAI-1 levels and improved clinical features, including lower C-reactive protein (CRP) levels." (PMID 32826331, 2020). "COVID-19 patients in the CVD group were older and had higher levels of troponin I (TnI), C-reactive protein (CRP), and creatinine." (PMID 32765943, 2020). "Neutrophils, C-reactive protein and several cytokines (as IL-6, TNF, IL-10) are increased in COVID-19, and this elevation is correlated with disease severity and death." (PMID 32733490, 2020). "Moreover, the number of immunosuppressive T-regulatory, T-reg (CD4+CD25+Foxp3+) cells and concentrations of IL-6, IL-10, and C-reactive protein (CRP) were up-regulated in patients with severe COVID-19, suggesting that SARS-CoV-2 infection may lead to “over-immunosuppression” in the case of obesity." (PMID 32650509, 2020). "ALT, C-reactive protein, neutrophils, AST, and lymphocytes counts have very good accuracy in predicting cases with positive RT-PCR for COVID-19 patients." (PMID 32823901, 2020). "Elevated plasma concentration of inflammatory mediators was observed in patients with COVID-19, including IL-6, IL-10, TNF-α, and other inflammatory cytokines, as well as ferritin and C-reactive protein." (PMID 33552062, 2020). "Compared with the younger patients, the older COVID-19 individuals had more chronic diseases and significantly elevated levels of WBC, neutrophil, and CRP levels." (PMID 32612961, 2020). "Recently, the traditional inflammation markers, such as C-reactive protein (CRP), ferritin, and cytokines, are considered as predictive markers for COVID-19 severity." (PMID 33251234, 2020). "Patients with COVID-19 AKI have also been reported to have higher levels of systemic markers of inflammation, particularly ferritin, C-reactive protein, procalcitonin and lactate dehydrogenase, than patients with COVID-19 and normal kidney function." (PMID 33060844, 2020). "Common laboratory abnormalities in COVID-19 patients include decreased white blood cell, lymphocyte, and platelet counts, and an increased LDH, CK, and CRP levels 7,8,9,10,11." (PMID 32226287, 2020). "It has been reported that parsimonious models, which contain five features (age, lactate dehydrogenase, C-reactive protein, CD4+ T-cell counts, and mass of infection), are an ideal measure for predicting COVID-19 severity." (PMID 32584780, 2020). "We confirmed high CRP levels and WBC/neutrophil counts as biological predictors of OTI requirement in patients with severe COVID-19 requiring hospitalization, in line with previous reports." (PMID 32708264, 2020). "We also observed that inflammatory markers, including elevated levels of CRP, ESR, and IL-6, were found both in patients with severe and mild COVID-19, with a significant increase detected in patients with severe COVID-19." (PMID 33163160, 2020).
COVID-19 (continued). "Here, increases in CRP, IL-6, and TNF-α levels in severe cases compared to mild cases of COVID-19 were revealed." (PMID 33244370, 2020). "Our data adds to the current knowledge, that amongst severe COVID-19-patients, NLR and relative neutrophilia more than CRP paralleled the observed short-term clinical course." (PMID 33106497, 2020). "Regarding laboratory data, a marked reduction in lymphocytes and elevation of the concentrations of CRP, LDH and hepatic enzyme are often observed in COVID-19 patients." (PMID 32894449, 2020). "A recent meta-analysis demonstrated an association between several inflammatory biomarkers (such as C-reactive protein (CRP), procalcitonin, interleukin (IL-6) and ferritin) with COVID-19 severity." (PMID 32922211, 2020). "Recently, we collaboratively reported that in the discarded serum of patients with COVID-19, the levels of NETs were increased and correlated with lactate dehydrogenase (LDH), D-dimer, and C-reactive protein (CRP) levels." (PMID 32993479, 2020). "The sensitivity of CRP, ESR, and decreased WBC was reported as high as 100%, 67%, and 80% of COVID-19 cases." (PMID 33294226, 2020). "The Spearman correlation analysis revealed that the presence of diabetes was positively correlated with age, hs-CRP, LDH, IL-6, CD8+ cells, and severity of COVID-19 and negatively correlated with CD3+ cell counts, CD4+ cell counts, and CD4+/CD8+ ratio." (PMID 33062712, 2020). "Levels of WBC, lymphocytes, neutrophils, CRP, NLR, PLR, troponin-I, creatinine, and BUN are important indicators for severity grading in COVID-19." (PMID 32612961, 2020). "Of the non-COVID-19 patients, 77.4% had normal WBC counts and 3% had lympho-neutropenia, while 19.3% had leukocytosis and 22.6% had high levels of C-reactive protein (CRP)." (PMID 33088398, 2020). "Our findings suggest maternal CRP levels may be associated with neonatal lung radiological changes, as antenatal CRP levels were higher in mothers of neonates who had abnormal radiological findings (with COVID-19 or without)." (PMID 32722722, 2020). "The odds of having abnormally low neutrophil count were lower in the HAdV patients than in the COVID-19 patients, but the odds of having higher-than-normal levels of hemoglobin, albumin, APTT, CRP, and procalcitonin were higher in HAdV patients." (PMID 33302983, 2020). "In COVID-19 cases, low levels of oxygen saturation (<88%), lymphocytopenia, D-dimer, ferritin, and AST, LDH, and CRP elevations are shown to be poor prognostic factors at different cut-off values ​​in different cohorts." (PMID 32599972, 2020). "While in patients with both SAA and CRP within the reference range no severe pneumonia occurred, in some of the patients with normal CRP but elevated SAA severe pneumonia was found, suggesting higher sensitivity of SAA for assessing COVID-19 severity." (PMID 33679725, 2020). "Increased inflammation -related indicators were found in patients with COVID-19, including erythrocyte sedimentation rate (ESR), interleukin-6 and C-reactive protein (CRP)." (PMID 32677918, 2020). "Therefore, higher neutrophil counts and CRP levels in cancer patients with COVID-19 may be the result of the combined effect of cancer and COVID-19, and lead to mutual promotion, and may also be the key to triggering a “cytokine storm” and leading to critical illness and mortality." (PMID 33192519, 2020). "There are limited data on how the trend of the inflammatory markers such as CRP, LDH, or ferritin affects the outcomes in COVID-19." (PMID 33133323, 2020). "Laboratory findings specific to COVID-19 include elevated prothrombin time, LDH (lactate dehydrogenase), D-dimer, ALT, C-reactive protein (CRP), and creatine kinase." (PMID 32328367, 2020). "The multivariate logistic regression analysis identified age, CHD, and the five laboratory variables, which included Lym%, PLT, CRP, LDH and D-dimer, as independent factors for the survival of COVID-19 patients." (PMID 33256643, 2020).
COVID-19 (continued). "SARS-CoV-2: A retrospective cohort study included patients with COVID-19 with moderate-to-severe ARDS and hyperinflammation (CRP ≥ 100 mg/L and/or ferritin ≥ 900 ng/mL)." (PMID 32982743, 2020). "COVID-19 Patients treated with KALETRA are more likely to show higher WBC counts and CRP serum levels than those who received ARB." (PMID 33317461, 2020). "Older COVID-19 individuals had more chronic diseases and significantly elevated WBC, neutrophil, and CRP levels." (PMID 32612961, 2020). "Laboratory tests, including CBC diff, CRP, and LDH, along with two PCR COVID-19 tests, should be performed at least 24 hours apart." (PMID 33123320, 2020). "Several indicators were identified by LASSO regression analysis as predictors for COVID-19 patients with a poor outcome including age, NLR, D-dimer and CRP." (PMID 32867787, 2020). "Compared with the results of CAP and normal control groups, the mean values of C3, C4, CRP, SAA and PA in the COVID-19 group (including mild, moderate and severe patients) showed significant changes (P < 0.01)." (PMID 32713370, 2020). "Increased CRP, ALT, TNI, and D-dimer levels and lymphocytopenia were present in most critical COVID-19 patients." (PMID 32589164, 2020). "C-reactive protein (CRP) and lactic dehydrogenase (LDH) were significantly higher in (+)COVID-19 patients." (PMID 32824683, 2020). "In our study, 4 markers (lymphocytes, neutrophils, CRP and ESR) were potentially important in predicting who will show positive PCR in COVID-19." (PMID 33738019, 2020). "The fact that the levels of C-reactive protein significantly decreased after treatment in the discharged group but not in the deceased group provides support that the dynamic changes of C-reactive protein may serve as good indicator of prognosis of the elderly patients with COVID-19." (PMID 32651993, 2020). "CT imaging presentation, lymphopenia, CRP, NLR, and PLR are significant indicators for severity grading of COVID-19." (PMID 32612961, 2020). "H7N9 patients had similar patterns of lymphopenia, neutrophilia, elevated alanine aminotransferase, C-reactive protein, lactate dehydrogenase, and those seen in H1N1 patients, which were all significantly different from patients with COVID-19 (P < 0.01)." (PMID 33261654, 2020). "In summary, the present study has shown the CBCs of 208 mild and common COVID-19 cases and the most likely laboratory findings in these patients were abnormalities in RBCs, HGB, HCT, and CRP." (PMID 32725148, 2020). "Ki-67 expression strongly correlated with CRP levels, and with systemic levels of the cytokines IL-6, MCP-1, IP-10 and IL-10, cytokines that were enhanced in COVID-19 patients and tracked with severity." (PMID 32943497, 2020). "COVID-19 patients with ARDS and MOF have elevated levels of IL-6 and C-reactive protein, which are characteristic indications of these severe conditions." (PMID 32722596, 2020). "Higher neutrophil count, C-reactive protein, and decreased lymphocyte count were present in non-survivors, and multiple logistic regression model showed that increased neutrophil count and lymphocytopenia were risk factors for in-hospital mortality in COVID-19." (PMID 32871887, 2020). "CRP is a nonspecific marker of inflammation which was widely used as a biochemical indicator for reflecting the acute severe systemic inflammatory response caused by a viral infection, such that our research illustrated that the severe COVID-19 patients had a high value than mild ones." (PMID 32571410, 2020). "C-reactive protein (CRP) and procalcitonin were significantly higher in confirmed COVID-19 patients, and classical chest radiograph appearances were more common in confirmed COVID-19 patients (p < 0.001)." (PMID 32905045, 2020). "Laboratory values for LDH, CRP, and IL-6 were significantly higher in the group of COVID-19-positive patients who developed ARDS compared to COVID-19 patients with mild clinical course." (PMID 33123171, 2020).
COVID-19 (continued). "A nomogram based on age, CHD, Lym%, PLT, CRP, LDH and D-dimer was established to accurately predict the prognosis of COVID-19 patients." (PMID 33256643, 2020). "The laboratory results showed that in most COVID-19 cases, lymphocyte counts, lymphocyte percentages, ESR, CRP, IgG, Fib, and cytokines all deviated from the normal ranges." (PMID 33251228, 2020). "NLR and CRP are established markers that reflect systemic inflammatory, and these parameters alter in patients with novel coronavirus (SARS-CoV-2) pneumonia (COVID-19)." (PMID 33244379, 2020). "High sensitivity was found in the case of C-reactive protein (CRP) for ICU requirement (0.92, 95% CI: 0.80–0.97) and severe COVID-19 (0.91, 95% CI: 0.82–0.96)." (PMID 33282888, 2020). "Acute phase proteins such as CRP, LDH, ferritin, procalcitonin, D-Dimer, ESR and IL-6 have also been well correlated with the disease severity, progression and poor outcome in COVID-19." (PMID 33225909, 2020). "In the current study, the AUC of CRP, ALT, LDH, urea and NEU were above 0.80; thus, they are effective and have very good predictive value for predicting COVID-19." (PMID 32259132, 2020). "Results showed that COVID-19 patients have higher serum level of cytokines (TNF-α, IFN-γ, IL-2, IL-4, IL-6 and IL-10) and CRP than control individuals." (PMID 32475230, 2020). "COVID-19 patients with ESS had stronger inflammatory responses, with higher levels of CRP and erythrocyte sedimentation rate as well as a higher positive rate of procalcitonin." (PMID 33117282, 2020). "Lymphocytopenia, thrombocytopenia, high C-reactive protein (CRP), high lactate dehydrogenase (LDH) and high ferritin levels were significantly more present in patients who died of COVID-19 in hospital, possibly reflecting a higher inflammatory state." (PMID 33246431, 2020). "High levels of LDH, C-reactive protein, neutrophils, and erythrocyte sedimentation rate (ESR) were also notable in COVID-19 patients." (PMID 32823901, 2020). "In COVID-19 patients inflammatory factors such as C–reactive protein (CRP) and erythrocyte sedimentation rate (ESR) are generally elevated, and CRP level, in general, positively correlates with the severity of the infection." (PMID 33382687, 2020). "Laboratory findings showed high lactic acid level (2.1 mmol/L) and C-reactive protein (CRP, 48.8 mg/L), and low white blood cell count (1.96 × 109/L), indicative of severe COVID-19." (PMID 32560646, 2020). "Our findings suggest that level of LDH, CRP, ALT and NEU can be used to predict the result of COVID-19 test." (PMID 32259132, 2020). "CRP showed a weak negative relationship with the time since recovery from COVID-19 (b = -0.025, p = 0.009)." (PMID 42110271, 2026). "Traditional inflammatory markers, including C-reactive protein (CRP), Interleukin-6 (IL-6), ferritin, and composite indices such as the Neutrophil-to-Lymphocyte Ratio (NLR) and the Prognostic Nutritional Index (PNI), have been studied extensively in COVID-19." (PMID 39857810, 2025). "We found that COVID-19 patients with diabetes had more severe inflammation with significantly higher WBCs, neutrophils, CRP, and procalcitonin than those without diabetes." (PMID 39886017, 2025). "As we show in the current study, combining information on CRP, albumin, RDW, and age in hospitalized COVID-19 patients results in a comprehensive, clinically relevant prognostic score that incorporates different aspects of thromboinflammation and chronic comorbidities." (PMID 40431641, 2025). "In COVID-19 patients, hyperglycemia at admission resulted in hypercoagulability, reflected by elevated D-dimer levels, and a heightened systemic inflammatory response, as evidenced by increased ESR, CRP, and ferritin levels." (PMID 40075801, 2025). "The findings of elevated inflammatory markers such as C-reactive protein (CRP) and neutrophil-to-lymphocyte ratio (NLR) in non-survivors align with previous studies demonstrating their association with COVID-19 severity and mortality." (PMID 41440513, 2025).